BRAF (B-Raf proto-oncogene, serine/threonine kinase)
Diseases named in the same sentence as BRAF in open-access papers (continued):
Sharing a sentence is not in itself a finding about the gene and the disease.
cancer (continued). "GEPs of 89 immunotherapy-naïve BRAF-CRCs were generated using the Pan-Cancer IO 360 gene expression panel and the NanoString nCounter platform and were correlated with microsatellite instability (MSI) status and with CD8+ tumor-infiltrating lymphocyte (TIL) content." (PMID 36010943, 2022). "The paradox breakers PLX8394 and PLX7904 are currently undergoing clinical trials and could prove more effective drugs for the treatment of class I BRAF-mutant cancers." (PMID 33367512, 2021). "Some phosphosites may be cancer-type specific: we uniquely observed BRAF p.S467/Y472 in BRCA and p.S465 in UCEC." (PMID 33875650, 2021). "Considering all types of cancers, hyperactive MAPK signaling occurs in over 85% of cancers, which is caused directly by genetic alterations of its upstream activators or components, including RTKs, RAS, and BRAF, or indirectly by other regulators of the pathway." (PMID 34164404, 2021). "Furthermore, N-terminal alternative splicing and overexpression of BRAF(V600E) were discovered in drug-resistant cancer patient samples." (PMID 35582307, 2021). "The expression of cancer-associated fibroblasts (CAF)-related proteins in cancer cells and stromal cells of PTCs were different according to histologic subtype, BRAF mutation status, and subtype of stroma, and such expression was associated with overall patient survival." (PMID 33669363, 2021). "Collectively, the findings suggest that studies should examine whether the blockade of the oncogenic mutations of RAS, BRAF, or PI3K in certain types of cancer, such as CRC, restore EREG expression that mediates the activation of EGFR downstream signaling." (PMID 34884633, 2021). "Although BRAF is one of the most frequently mutated genes in many cancers, it is interesting that BRAF does not directly interact with activated RAS." (PMID 34103089, 2021). "Both oncogenic signaling by the BRAF oncoprotein kinase and pathway-targeted therapeutics that inhibit BRAF signaling can have complex and context-dependent effects on autophagic flux in various cancer cell types." (PMID 34298710, 2021). "In particular, in case of mutation of both of them, cancer cells suppress apoptosis mainly thank to pTERT activity, while in case of mutation occurring only on BRAF gene, apoptosis activity seems to be not significantly affected." (PMID 34206867, 2021). "Furthermore, the cancer cell lines differ in KRAS, BRAF and PIK3CA mutations, which are known to directly affect metabolic reprograming through their involvement in the MAPK/ERK signaling pathway." (PMID 33671096, 2021). "Given that the oncogenic effects of the BRAF mutation are the same as those in human cancer, inhibitors targeting activation of the BRAF/MAPK pathway could also be effective for treating dog cancer as well as human cancer." (PMID 34502061, 2021). "SK-MEL-3 cells bear the mutation in BRAF (p.V600E) and PT53 genes (cancer cell line mutation data)." (PMID 34299117, 2021). "Anti‐EGFR or BRAF targeted therapies were not recommended in either pancreatic head or body/tail cancers because of the extremely low druggable mutation frequencies." (PMID 33452856, 2021). "The MAPK pathway is commonly activated in cancers by driver mutations in KRAS, NRAS, and BRAF." (PMID 34214079, 2021). "Through analyses of these cells and of human oncogenic KRAS-, NRAS- and BRAF-driven cancer cell lines we identified that resistance to single MEK inhibitor and ERK inhibitor treatments arise rapidly but combination therapy completely blocks the emergence of resistance." (PMID 33924486, 2021). "BRAF mutations in MSS cancers were associated with a poor prognosis, while the presence of BRAF mutations in MSI-H cancers had no prognostic effect." (PMID 34063682, 2021).
cancer (continued). "Moreover, in some cases, combined inhibition of oncogenic signaling plus autophagy has been shown to be an effective strategy for the treatment of cancers driven by oncogenic KRAS or BRAF both in preclinical models and in clinical trials." (PMID 34298710, 2021). "Along with the Ras-driven cancers, autophagy plays an oncogenic role in BRAF-driven melanoma." (PMID 33802014, 2021). "This review describes the relationship between BRAF-targeted therapy and autophagy regulation, and discusses possible future treatment strategies of combined inhibition of oncogenic signaling plus autophagy for BRAF-driven cancers." (PMID 34298710, 2021). "BRAF mutation was evaluated in 34 patients; 2 patients (5.9%) had BRAF mutant cancer." (PMID 34893673, 2021). "Thus, SHP2 inhibition, which links RTKs to the RAS–RAF–MEK–ERK and RAS–PI3K–AKT–mTOR pathways, will be ineffective in KRAS-mutant or BRAF-mutant cancer cell lines." (PMID 34790119, 2021). "Clinical significance: Since dabrafenib alone did not cause cardiac dysfunction, it may be preferable for use as monotherapy (rather than in combination with other drugs that are cardiotoxic) in some patients with BRAF directed cancers." (PMID 34296750, 2021). "BRAFV600E mutation is the most frequent BRAF mutation, but is not unique, and about 200 different types of BRAF mutant alleles have been identified in all cancers." (PMID 34063682, 2021). "LMS1 was further characterized by several oncogenic signatures in the MAPK and MET signaling pathways (including KRAS and BRAF signatures), as well as cancer aggressiveness (cell migration, hypoxia) and a signature of resistance to the standard chemotherapeutic agent 5-fluorouracil." (PMID 34470666, 2021). "What is the in vivo RAS dependency of BRAF alterations in cancer samples?" (PMID 33507258, 2021). "Finally, we tested a profile including EGFR and VEGFR2 as targets, due to the interest in them for cancer treatment, and tried again to design out binding to BRAF." (PMID 33530327, 2021). "Therefore, further studies investigating the safety and efficacy of combining an IGF1R inhibitor with BRAF and MEK inhibitorsare warranted in cancers harboring BRAF mutations and resistant to targeted therapies." (PMID 34831014, 2021). "The recent approval of BRAF inhibitors for CRC has improved cancer treatment outcomes." (PMID 34168268, 2021). "Therefore, in patients with KRas and BRaf mutant cancers, immune checkpoint blockade has presented as an additional avenue of treatment to consider and has even produced positive results in patients with these mutations." (PMID 34680208, 2021). "A blockade of ERK could cause patients to overcome or postpone resistance to inhibitors of upstream kinases like MEK and BRAF, which could benefit a larger range of patients suffering from cancer." (PMID 34692523, 2021). "The subtype cancer of the BRAF mutant usually benefits from inhibitors targeting this mutation." (PMID 34745259, 2021). "However, additional isoforms for BRAF (NM_001354609, XM_017012558, and XR_001744857) emerged in both primary cancer and the corresponding metastasis, and all contained the V600E variant." (PMID 33907296, 2021). "Moreover, we identified well-known vulnerabilities in cancer, such as MAPK1 dependency in BRAF mutated cells." (PMID 34454516, 2021).
cancer (continued). "Herein, our study reveals the impact of COL11A1 gene product in the alteration of PTEN, PIK3CA, KRAS, and BRAF which might downregulate the RTK-RAS-PI3K signaling pathways to induce cancer development." (PMID 33597969, 2021). "The OncomineTM Pan-Cancer Cell-free NGS assay is designed to detect 982 hotspots in comparison to the targeted approach for the reference ddPCR test which interrogates specific EGFR, KRAS and BRAF mutations." (PMID 33494470, 2021). "When these mice were crossed with TSH receptor knockout mice, the BRAF mutation was not able to induce cancer." (PMID 34256769, 2021). "Alterations in BRAF, RAS, RET/PTC, and TERT promoters are assumed as “driver” changes and could be used as diagnostic markers for cancer development." (PMID 34684168, 2021). "These authors also indicated that elevated CRAF protein levels may similarly contribute to primary insensitivity to inhibition in a subset of BRAF-mutant cancer cells." (PMID 33474634, 2021). "CRAF overexpression appears to be a common event in BRAF inhibitor resistance but is not commonly mutated in cancers." (PMID 34831420, 2021). "Likewise, the RAF kinase predominantly altered in cancer, BRAF, can act independently from upstream RAS signaling." (PMID 32545208, 2020). "Conversely, BRAFV600E knock-in mice (BRAF-Lox/TPO-Cre) generated PTC-like cancers." (PMID 31936153, 2020). "It is possible that APC mutations, in the context of BRAF mutation, facilitate an exit to oncogene induced senescence and while simultaneously satisfying the requirement for WNT signaling, facilitating a rapid transition to dysplasia and invasive cancer." (PMID 32384699, 2020). "In addition, the American Society of Clinical Oncology (ASCO) and the National Comprehensive Cancer Network (NCCN) suggest that the BRAF gene to be evaluated prior making treatment decisions for patients with cancers." (PMID 33247675, 2020). "By contrast, a small amount of CRCs harbor a BRAF mutation but remain microsatellite-stable (MSS), resulting in a worse prognosis than BRAFmt/MSI cancers; however, molecular characterization and predictive value of this particular subgroup has not yet been fully clarified." (PMID 32015690, 2020). "The higher proportion of cancers bearing both APC and BRAF mutation in the present study may be due to selection bias in the present series, with a higher proportion of late stage microsatellite stable cancer included." (PMID 32384699, 2020). "We find that common cancer mutations including BRAF-V600E and KRAS-G12D are predicted to bind none of the common HLA alleles, and are thus “immunogenically silent” in the human population." (PMID 32256484, 2020). "Importantly, PTEN and BRAF are also co-altered more often than expected in cancer patients queried through cBioPortal (OR 1.86, p value < 0.001)." (PMID 32907621, 2020). "In our study, we investigated the MEK inhibitor selumetinib and PI3K/mTOR dual inhibitor BEZ235 alone and in combination in BRAF-only mutant and BRAF + PI3K/PTEN double mutant cancer cells using short- and long-term 2D viability assays, spheroid assays, and immunoblots." (PMID 33081092, 2020). "BRAF mutants are found in up to 9% of all human cancers and over 50% of melanoma." (PMID 32873792, 2020). "We hypothesize that WNT signaling activation in BRAF mutant cancers will be heterogeneous, and a mosaic of alterations underpin WNT signaling to achieve a “just-right” level of pathway activation." (PMID 32384699, 2020). "Therefore, the BRAF pathway has become a molecular target for individualized cancer therapy, with promising results deriving from clinical trials." (PMID 32879641, 2020). "The mechanisms associated with APC mutation induced aggressiveness in the context of BRAF mutant cancers are not clear." (PMID 32384699, 2020).
cancer (continued). "Moreover, A2058 has an oncogenic mutation of the valine-to-glutamic acid substitution at position 600 (V600E) of v-raf murine sarcoma viral oncogene homolog B1 (BRAF) that makes it resistant to anti-cancer drug dacarbazine." (PMID 32560478, 2020). "Another example is the BRAF V600E mutant which is found in many cancer types." (PMID 32069833, 2020). "As is the case with PI3K, BRAF mutation-mediated activation allows a significant proportion of the RAS downstream signaling to be activated, sufficient for supporting the growth of specific cancer types and being an attractive potential drug target." (PMID 32545208, 2020). "The analysis revealed that in BRAF FOXE1+/− cancers, the decrease of all the analyzed thyroid differentiation markers is significantly more pronounced than that observed in BRAF FOXE1+/+ ones, showing that lower FOXE1 levels are associated with less differentiated tumors." (PMID 33375029, 2020). "Furthermore, cancer cell dedifferentiation and histone methylation were attributed to resistance following BRAF inhibitor treatment." (PMID 32042336, 2020). "In addition, despite an initial response, BRAF-driven cancer cells can become resistant to BRAFV600E kinase inhibition." (PMID 32878084, 2020). "Regarding its impact on prognosis, CRC patients with BRAF exon 15 p.V600E mutations show lower OS, DFS, and cancer-specific survival (CSS) rates than wild-type patients, despite the stage of the disease (II or III) or the adoption of chemotherapeutic regimens after surgery." (PMID 33260892, 2020). "A plausible explanation is that Src or BRAF are likely one of the multi-drivers in some cancers." (PMID 32069833, 2020). "Notably, BRAF mutations reduced FAM134B expression in CRC, suggesting that FAM134B has downstream interactions with BRAF-associated cancer pathways." (PMID 33199694, 2020). "Although BRAF inhibitors have been approved by the Food and Drug Administration, their therapeutic benefits for cancer patients with BRAF protein mutations are still not obvious." (PMID 32033142, 2020). "Taking into account the positive binding results obtained in the docking studies to the BRAF-ATP model and the promising cytotoxicity shown in several cancer cells, we next explored the effect of compounds with IC50 near to that of sorafenib (1, 2, 3, 4, 9, and 52) on the MAPK/ERK pathway." (PMID 33371382, 2020). "Consequently, inhibiting BRAF kinase signalling is an attractive target, which can benefit patients across different cancer types." (PMID 32411231, 2020). "In the multivariable analysis (Model 1), the positivity of the D-marker panel remained an independent risk factor for cancer progression after adjusting for cancer differentiation, KRAS mutation, and BRAF mutation, and the adjusted hazard ratio (HR) (95% CI) was 1.52 (1.09 to 2.11)." (PMID 32532105, 2020). "In addition, several reports have showed that some gene mutations, like BRAF mutation and ERBB2 mutation, were associated with MSI status in several cancer types." (PMID 33178590, 2020). "According to the database of COSMIC, the world's largest and most comprehensive resource for exploring the somatic mutations in human cancer, chromosome 7 consists of lots of well-known cancer-related somatic mutations, including EGFR, BRAF, CDK6, MET, T1F1, and so on." (PMID 32695679, 2020). "However, Ras-mutated cancers possess intrinsic resistance to both RAF and MEK inhibitors, and even BRAF (V600E)-harboring cancers develop acquired resistance after 6–10 months treatment." (PMID 32807225, 2020). "One might assume that all patients with BRAF mutant cancer would benefit from treatment with BRAF inhibitors." (PMID 33043759, 2020).
cancer (continued). "APC was mutated in 82% of these cancers, in comparison to just 28% of BRAF mutant cancers." (PMID 32384699, 2020). "Based on five relationship predictive methods provided by the UbiBrowser online tool, some potential targets were found and many of the substrates of these five E3 ubiquitin ligases, such as proteins in the JAK family, AKT1 and BRAF, are well-known oncoproteins in multiple cancer types." (PMID 33232269, 2020). "Because some patients with a BRAF mutation in malignant tumors do not respond well to conventional chemotherapy, people are starting to focus on MAPK pathway target inhibition." (PMID 32476297, 2020). "We did find an indication that the geometric mean SUVpeak per patient may be related to OS in a small subgroup of only left-sided BRAF wild-type cancer patients, adjusted for potential confounders." (PMID 31705176, 2020). "Previous studies demonstrating a constitutive fragmented mitochondrial morphology in oncogenic KRAS or BRAF driven cancers prompted us to seek whether such endogenously activating mutations in colorectal cancerous cell lines have any role in tumorigenesis." (PMID 33738242, 2020). "The BRAF-negative serrated adenoma (AC43) displayed a truncating ATM mutation shared with the matched carcinoma." (PMID 32895052, 2020). "Compared to conventional carcinomas, SACs are characterized by a worse prognosis, weak development of the immune response, an active invasive front and a frequent resistance to targeted therapy due to a high occurrence of KRAS or BRAF mutation." (PMID 32183342, 2020). "Contrary to BRAF inhibition-resistant cells, the development of resistance to imatinib in various cancers has been linked to increase in glycolysis rather than mitochondrial metabolism." (PMID 35582564, 2019). "This analysis demonstrates that oncogenic BRAF expression can oppose expression of mature glia gene programme, indicating that dynamics of BRAF expression may contribute to heterogeneity in cancer cell states found in PAs." (PMID 31427603, 2019). "Moreover, the role of missense APC mutations, which are relatively frequent in serrated lesions and BRAF mutant cancers with MSI, should be further investigated in the serrated pathway." (PMID 31330830, 2019). "As the MEK/ERK pathway is widely activated, as a result of RAS or BRAF mutations and others, in human cancer cells, our finding provides a reasonable explanation for widespread transcriptional overexpression of UHRF1 (DNMT1 as well) in various cancers." (PMID 30696879, 2019). "Several reports support this possibility and thus, SHOC2 could also provide a useful target for combination therapies against BRAF-mutant cancers in some contexts." (PMID 31182717, 2019). "Moreover, increased DNFA pathway expression appears to be intrinsic to malignant cancer cell types independently of onco-drivers, including constitutively active BRAF mutants." (PMID 31316083, 2019). "BRAF-mutated mCRC show distinct clinical features and poorer survival than BRAF wild-type cancers." (PMID 31319569, 2019). "Specifically, in CRC, a recent comprehensive analysis of 2.314 cases showed how the frequency of kinase gene fusions in an unselected population is about 0.9%, but it significantly increases in MSI-high (MSI-H) tumors (5%) and overall in RAS/BRAF wild type cancers (15%)." (PMID 31731495, 2019). "In a basket study with vemurafenib in BRAF V600E mutation-positive non-melanoma cancers, the objective response rate in BRAF-mutant gliomas was 25%." (PMID 30984614, 2019). "Similarly, in BRAF mutant cancers, combined inhibition of BRAF with other members of the MAP kinase family, such as MAPK1-MAPK3 and MAP2K1-MAP2K2, overcomes emergent mechanisms of resistance." (PMID 31300006, 2019). "Indeed, constitutive activation of ERK1 and ERK2 signaling is frequently observed in human cancers due to mutations in genes that encode RTKs, RAS, BRAF, CRAF, MEK1, and MEK2." (PMID 30487597, 2019).